IL6 (interleukin 6)
Diseases named in the same sentence as IL6 in open-access papers (continued):
Sharing a sentence is not in itself a finding about the gene and the disease.
breast cancer (continued). "Additionally, invasion is directly proportional to IL-8 expression in several breast cancer cell lines and its expression in breast cancer appears to be induced by other cytokines (IL-1β, TNFα and IL-6), an/or hormones (progesterone and estrogen)." (PMID 37979099, 2024). "Also, the expression of the cytokines IL-6, IL-8, and IL-10 in the breast cancer cells increased following exposure to P. acidilactici and its CFS for 24 and 72 h." (PMID 38314029, 2024). "Furthermore, breast cancer patients with a combined high tGAS+IL-6/IL-6R/GP130 activation had worse MFS when compared to patients with low tGAS+IL-6/IL-6R/GP130 activation." (PMID 39768178, 2024). "Meanwhile, IL-6, and its associated STAT3 signaling, has recently gained attention as an inflammatory cytokine facilitating the formation of a (pre)metastatic niche for solid malignancies, including breast cancer." (PMID 39128004, 2024). "Another interleukin targeted by miRNAs in breast cancer is IL-6." (PMID 38726321, 2024). "Interleukin (IL)-6 can play a key role in the growth and development of cancer cells, in the formation of osteolysis and humoral hypercalcaemia, and in the regulation of oestrogen production in breast cancer cells." (PMID 38956273, 2024). "The KM survival curves showed that CD46, JAG1, IL6, and IL6R were all risk factors that lead to poor prognosis in breast cancer patients, which implies that the enhanced interaction between CD46-JAG1 leads to poor prognosis in breast cancer patients, along with the IL6-(IL6R+IL6ST) axis." (PMID 38571938, 2024). "In addition, chronically elevated IL-6 levels are associated with the formation and growth of several tumors such as breast cancer, making IL-6 a cancer marker, leading to a great need for novel IL-6-lowering cancer immunotherapy approaches." (PMID 38388989, 2024). "Previously, it has been demonstrated that in MCF7 breast cancer cells, STAT3 collaborates with FRA1 and c-JUN AP1 components to activate the MMP9 promoter, while in HepG2 hepatoma cells, STAT3 associates with HDAC1 to inhibit IL6-induced CCL2 transcription." (PMID 39274912, 2024). "Increased OSM or IL-6 expression correlates with reduced survival in breast cancer patients." (PMID 38236642, 2024). "The application of IL-6 on breast cancer cells inhibits proliferation in estrogen receptor-positive cells, while high circulating IL-6 levels are correlated with a poor prognosis in breast cancer patients, indicating discrepancies and the distinct roles of this cytokine." (PMID 39126001, 2024). "Similarly, in the MMTV-PyMT mouse model of breast cancer metastasis, IAV-induced proliferation of PyMT+ small lesions and formation of micro-metastases in the lungs was dampened by IL-6 deficiency." (PMID 38645169, 2024). "High IL-6 levels in breast cancer tissues maintain the aggressive phenotype." (PMID 36835413, 2023). "HSPB1 overexpression led to decreased expression of IKβ-α (a negative regulator of NF-κB) and increased expression of NF-κB, p-IKβ-α, and downstream molecules of NF-κB (Twist1, IL6, and Survivin) in breast cancer cells, indicating the potential role of HSPB1 in regulating NF-κB activity." (PMID 37454220, 2023). "IL-6, IL-8 and CCL-2 cytokines are mediators of tumour invasion and metastasis, and their increased levels are associated with cancer stem cell (CSC) enrichment and greater tumour stage and grade in breast cancer." (PMID 36674737, 2023). "Wnt signalling within adipocytes promotes stemness, as demonstrated in breast cancer where adipocyte-secreted IL-6 and leptin activate breast cancer stem cells through Notch, Wnt, and Sex determining region Y-box 2/octamer binding transcription factor 4/Nanog signalling." (PMID 38136392, 2023). "Additionally, patients with liver metastases from breast cancer exhibited notably elevated levels of IL-6." (PMID 37507468, 2023).
breast cancer (continued). "In addition, RANTES and proinflammatory cytokines such as IL-6 can produce a more aggressive phenotype in breast cancer cells via AKT or STAT3 signal pathways." (PMID 37298699, 2023). "Thus, in patients with breast cancer, a poor response to radiotherapy correlates with IL-6 and p-STAT3 levels." (PMID 36635302, 2023). "In addition, adipocytes co-cultured with breast cancer cells can promote the invasion of tumor cells by overexpressing the inflammatory cytokines such as IL-6, TNFα, and MMPs." (PMID 37666813, 2023). "Therefore, cryo-thermal therapy combined with anti-IL-6 treatment was performed in a mouse model of breast cancer, resulting in a significantly improved overall survival rate." (PMID 37108179, 2023). "Moreover, in patients with breast cancer, a poor radiotherapy response correlated with high IL-6 and p-STAT3 levels." (PMID 36635302, 2023). "Recent studies have compiled evidence indicating that the IL-6 cytokine family (soluble factors) may be used for early and more precise breast cancer diagnosis and for designing targeted therapy to treat or even prevent metastasis development." (PMID 37817809, 2023). "In the present study, IL-6 was reduced after asiaticoside treatment in breast cancer cells." (PMID 36903346, 2023). "Macrophages secrete S1P, IL-6 and TNFα, thereby promoting breast cancer metastasis." (PMID 36670988, 2023). "In addition, HSPB1 overexpression led to enhanced secretion of IL6, which further facilitated breast cancer progression." (PMID 37454220, 2023). "Importantly, the IL-6 level correlated significantly with worse disease-free survival of patients with breast cancer." (PMID 36635302, 2023). "Also, both bone-metastatic myeloma and breast cancer cells are able to stimulate the production of IL-6 by bone marrow stromal cells, resulting in increased osteoclast differentiation and bone destruction." (PMID 37127752, 2023). "Besides the studies that have demonstrated utility in measuring both IL-6 and IL-8 individually in breast cancer and pancreatic cancer, the IL6/IL8 ratio is also an important factor that is currently being used to indicate disease outcomes." (PMID 37181043, 2023). "Next, we evaluated the influence of secreted IL6 on the malignant behaviors of breast cancer." (PMID 37454220, 2023). "In our study, female dogs with mammary cancer had higher serum levels of IL-6 than healthy ones." (PMID 36899784, 2023). "It has been reported that IL-6 can promote the progression of breast cancer and transfer." (PMID 36755259, 2023). "The importance of HIIT for breast cancer patients may stem in part from its anti‐inflammatory mechanisms, achieved through the down‐regulation of pro‐inflammatory factors such as IL‐6, and the up‐regulation of anti‐inflammatory factors like IL‐10 and TNF‐α." (PMID 37587859, 2023). "Narasin inhibits TGF‐β/SMAD3 and IL‐6/STAT3 activation in breast cancer cells." (PMID 37864240, 2023). "However, breast cancer cells display activation of NF-κB and upregulation of expression of IL-6, TGF-β, VEGF, and matrix-metalloproteinase 9 (MMP9)." (PMID 37822929, 2023). "Therefore, this study aimed to elucidate the underlying molecular mechanism of IL-6 in regulating KDM2A expression in CAFs and KDM2A-mediated paclitaxel resistance in breast cancer." (PMID 37821959, 2023). "For instance, co-culture of preadipocytes with breast cancer cells induced their invasion, migration, and proliferation, which was mediated by preadipocyte-secreted IL-6; blocking IL-6 signaling significantly blocked preadipocyte-induced proliferation, migration, and invasion." (PMID 36635302, 2023). "Recent research has revealed that exercise may significantly exhibit decreased post-operative IGF-1, CRP, TNFα, and Il-6 levels in adult and older adult women with breast cancer." (PMID 37958310, 2023). "Moreover, Sdc-1 directly mediates IL6-dependent effects on breast cancer cell adhesion and migration." (PMID 36980251, 2023).
breast cancer (continued). "Importantly, the fraction of breast cancer cells that survived after irradiation increased significantly after IL-6 treatment in a concentration dependent manner." (PMID 36635302, 2023). "CAAs secrete a variety of inflammatory and cancer-related adipokines such as tumor necrosis factor-α, interleukin-6 (IL-6), and plasminogen activator inhibitor-1 that can increase breast cancer cell proliferation, invasion, metastasis, and therapeutic resistance." (PMID 37880751, 2023). "The invasion ability of breast cancer cells, which was reduced by adipocyte-Grem2, was greatly restored by IL-6 treatment alone, but additional administration of Serpine1, another cytokine reduced by adipocyte-Grem2, had a greater effect on recovering cancer cell invasion." (PMID 37880751, 2023). "Breast cancer orthotopic xenograft model was constructed with EO771 cells transduced with empty vector or cSERPINE2 overexpression vector followed by intraperitoneal injection of IgG or anti-IL-6 antibody." (PMID 36797769, 2023). "IL-1β has been reported to control tumor invasion, up-regulate the initiation and development of primary tumor, increase the aggressivity of luminal breast cancer cells, and increase IL-6 production through NF-κB pathway leading to tumor growth and aggressiveness." (PMID 36835413, 2023). "The supernatants from HSPB1 overexpressing cells led to increased migration ability of breast cancer cells and tube formation of HUVECs, while the supplement of IL6 neutralizing antibodies could partly attenuate the promoted effect." (PMID 37454220, 2023). "Additionally, via the NF-kB/IL-6/JAK2/STAT3 pathway inhibition in breast cancer cells, we recently demonstrated the anticancer activity of azilsartan." (PMID 36611978, 2023). "Moreover, in an inflammatory tumor microenvironment, IL-1β stimulates IL-6 production, which can increase the aggressiveness of luminal-type breast cancer cells." (PMID 37569777, 2023). "IL-6, for example, regulates estrogen production in breast cancer cells and tissues." (PMID 36903346, 2023). "However, more recent research has shown that IL-6 activates STAT3 in ER-expressing breast cancer cells and increases its invasive and metastatic activity." (PMID 37834225, 2023). "Investigations on how EV-induced IL-6 upregulation within each breast cancer subtype TME may determine the tipping point between protumour and antitumour effects are warranted." (PMID 37441083, 2023). "According to several studies, raised levels of cytokine-mediated acute phase C-reactive protein, and pro-inflammatory cytokines, including IL-6, IL-1β, and TNF- α are found in breast cancer patients, documenting that breast cancer is associated with inflammation." (PMID 36978815, 2023). "This subpopulation could be related to resistant cells maintained by IL-6 in some breast cancer treatments." (PMID 38001682, 2023). "To further assess the anti-inflammatory effect of BTP2 on the breast cancer cells, we examined whether the LPS-induced upregulation of the inflammatory cytokines IL-6 and IL-8 in the MDA-MB-231 cells would be affected by the BTP2 treatment." (PMID 37371732, 2023). "Next, whether reduced expression and secretion of IL-6 in Grem2-overexpressing adipocytes had a direct effect on the proliferation of breast cancer cells was determined." (PMID 37880751, 2023). "Indeed, we find that vehicle-treated ErbB2-induced breast cancer tissue expresses Il1a, Il1b, Il6, and Nfkb1 at a measurable level." (PMID 37098526, 2023). "Also, a substantial increase (p < 0.001) in the levels of IL-6 was observed in prostate and breast cancer patients when compared to the healthy controls." (PMID 37153524, 2023). "Moreover, the IL-6/STAT3 signaling pathway was highlighted as one of the first potential targets for Manuka honey-induced breast cancer cell suppression." (PMID 36978815, 2023).
breast cancer (continued). "Likewise, CAAs cocultured with breast cancer cells have been shown to increase their expression of MMP-11 as well as proinflammatory cytokines (IL-6 and IL-1β) and thereby promote tumor cell invasion and metastasis." (PMID 36670988, 2023). "Collectively, these observations indicated that HSPB1 could aggravate the progression of breast cancer through promoting IL6 secretion." (PMID 37454220, 2023). "Previously, we found that Jaeumganghwa-tang (JGT), a mixture of 12 herbs commonly and safely used in Asian countries for a wide range of ailments, reduced IL6 expression in mammary tumors and increased sensitivity to tamoxifen therapy in vitro and in an animal model." (PMID 36980301, 2023). "Instead, the PPMPs enhanced IL-6 secretion and the cell cycle of breast cancer cells." (PMID 37069244, 2023). "However, activation of the STING pathway also enhances the IL-6-dependent survival of chromosomally unstable breast cancer cells, suggesting a pro-tumorigenic effect of cGAS-STING signaling." (PMID 37816954, 2023). "Using a Bcl-2 antagonist (sabutoclax) could inhibit the IL-6/STAT3 signaling to resensitize Dox-resistant breast cancer in vitro and in vivo models." (PMID 37480115, 2023). "Taken together, these results suggest that Grem2-overexpressing adipocytes have the potential to suppress the expression of cytokines, including IL-6, in adipocytes or breast cancer cells, which may contribute to the inhibition of breast cancer progression." (PMID 37880751, 2023). "IL-6 was shown to promote or inhibit the growth of breast cancer cells." (PMID 36980857, 2023). "We found that moderate amounts of PPMPs significantly accelerated the cell cycle of cancer cells and enhanced the secretion of interleukin 6 (IL-6) in the human breast cancer cell lines, MDA-MB-231 and MCF-7; however, cellular migration and motility were not altered." (PMID 37069244, 2023). "Similarly, inhibition of IL-6 can lead to the suppression of colony formation, reduction of cell survival, and repression of tumor growth in breast cancer." (PMID 36687217, 2023). "Moreover, IL-6 neutralizing antibody treatment blocked the CAF-induced increase in the clone number of breast cancer cells significantly." (PMID 36635302, 2023). "IL6 has also been reported to induce macrophage polarization to the M2-phenotype in various cancers, however, the association between HSPB1 and M2 polarization in breast cancer needed to be further elucidated." (PMID 37454220, 2023). "We selected the top two downregulated cytokines from the RNA-seq data, namely granulocyte colony-stimulating factor (G-CSF or CSF3) and interleukin-6 (IL-6), both of which have been reported to support breast cancer growth in various ways, and confirmed their downregulation by RT-qPCR." (PMID 38250802, 2023). "In conclusion, our study has identified key secretory factors (IL-6 and G-CSF) as mediators of taxane-induced dormancy awakening in a breast cancer model and a meta-analysis of 10-gene signature predicting recurrence free survival outcomes in patients receiving chemotherapy." (PMID 37699010, 2023). "Additionally, the siRNA-mediated knockdown of TLR4 suppresses the proliferation and release of the inflammatory cytokines, IL-6 and IL-8, in breast cancer cells." (PMID 37371732, 2023). "IL-6 has been identified to promote tumorigenesis and metastasis in breast cancer." (PMID 38201482, 2023). "Therefore, we further investigated the effect of HSPB1-induced IL6 in the progression and immune infiltration of breast cancer." (PMID 37454220, 2023). "For example, Lactobacilli R389 fermented milk could delay breast cancer growth by reducing serum IL-6 and increasing IL-10 in breast and tumor-infiltrating immune cells." (PMID 37221044, 2023).
breast cancer (continued). "Thus, in many cancers such as breast cancer, cytokines including leptin, IL-1B, IL-6, IL-8, IL-23, IL-17, and IL-10 stimulate while others including IL-2, IL-12, and IFN-γ, inhibit cancer proliferation and/or invasion and enhance the body’s anti-tumor defense." (PMID 36835413, 2023). "Besides, it has been reported that Zn2+ levels affect IL-6 in DMBA-induced breast cancer in female rats." (PMID 36970418, 2023). "Adipocyte-derived IL-6 and leptin promote breast cancer metastasis by activating the Janus kinase (JAK)/signal transducer and activator of transcription 3 (STAT3) and phosphoinositide 3-kinase (PI3K)/protein kinase B (AKT) signaling pathways, thus upregulating lysyl hydroxylase (PLOD2) expression." (PMID 36624542, 2023). "Moreover, another study focused on the effect of an anti-inflammatory diet, revealed a positive relationship between IL-6 and BMI in breast cancer patients." (PMID 37181043, 2023). "For women with breast cancer, IL6 (b = 2.469, 95% CI [− 7.614, 12.552], p = 0.631) and TNFα (b = 0.036, 95% CI [− 6.345, 6.418], p = 0.991) were not statistically significant moderators of the effect of exercise intensity on changes in muscle strength (Model 1.2)." (PMID 36658635, 2023). "Interestingly, the expression of IL-6 in breast cancer cells was significantly reduced by co-culture of adipocytes-Grem2." (PMID 37880751, 2023). "In conclusion, breast cancer and pancreatic cancer are two distinctive cancer types with several common characteristics in aspects of gene, hormone, and inflammatory biomarkers such as IL-6, CD4 or CD8 cells, VEGF and IDO-1." (PMID 37181043, 2023). "Given the obvious effect of HSPB1 on the expression of IL6 in breast cancer cells detected by our above results, we further investigate whether the secretion of IL6 could be influenced by HSPB1." (PMID 37454220, 2023). "MSCs exert their influence on the breast cancer stem cell pathway by secreting IL-6 and generating factors originating from mesenchymal cells, which may underlie the mechanism of MSC-BCSC mediation in breast cancer drug resistance." (PMID 38001753, 2023). "Since the PPMPs promoted the cell cycle of breast cancer cells, we evaluated whether the secretion of IL-6 was increased in cancer cells exposed to 1.6mg/ml PPMPs." (PMID 37069244, 2023). "In addition, positive feedback of CD73 with IL-6 (interleukin 6) has been reported in human breast cancer." (PMID 37835536, 2023). "Notably, IL-6 can induce resistance development in breast cancer cells against cytotoxic drugs intended for ERα+ breast cancer (like paclitaxel and doxorubicin) and anti-HER2+ breast cancer treatment, like Herceptin." (PMID 38001753, 2023). "When conducting a systematic research review, Salignan’s team proved that increased symptoms of fatigue, especially in women in early stages of breast cancer, were caused by increased concentrations of IL-6 and TNF, and of IL-1β during chemotherapy, and of IL-6 during radiotherapy." (PMID 36834426, 2023). "PPMPs attached to the cell membrane or inserted between cells may alter the physical contact or stimuli in human breast cancer cells, followed by the enhancement of cancer progressions, such as the cell cycle and IL-6 secretion." (PMID 37069244, 2023). "Considering our previous results showing that cats with mammary carcinoma have higher circulating levels of several immunomodulatory molecules (IL-6, TNF-α, CTLA-4, PD-1, PD-L1, VEGF-A, VEGFR-1, VEGFR-2, and LAG-3), the serum TIM-3 levels were evaluated to check for statistical correlations." (PMID 36672332, 2023). "Interleukins like IL-6, IL-1, and IL-11, trigger breast cancer (BC) development and invasion." (PMID 37675062, 2023). "In this study, IL6 was reported to induce a self-reinforced senescence/inflammatory milieu responsible for the epithelial plasticity and stemness features which prone to a more aggressive phenotype in breast cancer." (PMID 35924148, 2022).